TMPRSS4 (transmembrane serine protease 4)
Diseases named in the same sentence as TMPRSS4 in open-access papers (continued):
Sharing a sentence is not in itself a finding about the gene and the disease.
cancer (continued). "In TC, upregulated TMPRSS4 accelerated cancer cell proliferation by mediating CREB phosphorylation." (PMID 36380313, 2022). "Altered TMPRSS4 expression across human cancers may result from different data collection manner in diverse studies or distinct underlying biological mechanisms." (PMID 36380313, 2022). "TMPRSS4 was increased in most cancers from the Oncomine database compared with normal tissue." (PMID 36380313, 2022). "We found that the predictive role of TMPRSS4 for prognosis varied in different types of cancers." (PMID 36380313, 2022). "In addition, analysis of the Cancer Cell 2010 dataset showed that TMPRSS4 expression was significantly correlated with expression of SOX2 (rho = 0.484, P = 3.48e-10) and TWIST1 (rho = 0.368, P = 3.491e-06)." (PMID 34809669, 2021). "TMPRSS4 has been shown to be upregulated in various cancers and is regarded as a proto-oncogene." (PMID 34281234, 2021). "Next, we explored the molecular mechanisms by which TMPRSS4 promotes cancer stem–like properties." (PMID 34809669, 2021). "Acquisition of cancer stem–like properties by TMPRSS4 was examined by monitoring anchorage-independent growth, tumorsphere formation, aldehyde dehydrogenase (ALDH) activation, and resistance to anoikis and drugs in vitro and in an early metastasis model in vivo." (PMID 34809669, 2021). "Furthermore, we demonstrated that TMPRSS4 promotes both the invasion and proliferation of cancer cells through activation of AP-1 and subsequent upregulation of SLUG in a manner dependent on MAPKs." (PMID 34809669, 2021). "Together, these data suggest that the TMPRSS4/TWIST1–SLUG/SOX2 axis could be exploited as a target for anti-cancer therapy." (PMID 34809669, 2021). "These previous findings led us to hypothesize that TMPRSS4 drives diverse cellular functions beyond tumor invasiveness during cancer progression." (PMID 34809669, 2021). "Furthermore, TMPRSS4 promoted cancer cell survival and drug resistance, and both compounds enhanced anoikis sensitivity as well as reduced bcl-2 and survivin levels." (PMID 31292507, 2019). "Furthermore, we demonstrated that TMPRSS4 induces both the invasion and proliferation of cancer cells through AP-1 activation and subsequent upregulation of Slug and cyclin D111." (PMID 31292507, 2019). "Our previous observation that AP-1 and Sp1 are activated by TMPRSS4 led us to anticipate that TMPRSS4 may modulate cancer cell survival and that inhibition of TMPRSS4 may be an efficient therapeutic strategy for cancer treatment." (PMID 31292507, 2019). "Using HCT116 and SW620 cells, we again demonstrated that TMPRSS4 promoted cancer cell migration and invasion while TMPRSS4 moderately modulated cancer cell proliferation in a cell type- or context-dependent manner, which is consistent with our previous results." (PMID 31292507, 2019). "We also examined whether KRT1853 and IMD-0354 influenced the survival of TMPRSS4-positive cancer cells." (PMID 31292507, 2019). "The recent studies showed that TMPRSS4, which is kind of TTPs family and frequently overexpressed in the cancer cells, function as a cancer treatment target biomarker through the use of Cancer gene therapy (CGT) strategies." (PMID 31244309, 2019). "Most studies until know have focused on its implication in different cancers, where a growing body of evidence indicates that over-expression of TMPRSS4 among other effects enhances EMT-like process and induces migration two events that has been described to occur in IPF." (PMID 29529050, 2018). "Therefore, additional other region studies analyzing TMPRSS4 expression and cancer prognosis are needed to verify our results." (PMID 27344186, 2016). "High TMPRSS4 expression could promote cancer progression and is implied as a poor prognoses marker in solid tumor patients." (PMID 27344186, 2016). "The TMPRSS4/AP-1/Slug axis might be exploited as a target for potential anti-cancer therapy, possibly targeting both cell proliferation and migration." (PMID 27385093, 2016).
cancer (continued). "This study demonstrates that TMPRSS4 modulates both invasion and proliferation via Slug and cyclin D1, which is a previously unrecognized pathway that may regulate metastasis and cancer progression." (PMID 27385093, 2016). "TMPRSS4 (Transmembrane protease serine 4) is up-regulated in a broad spectrum of cancers." (PMID 26190376, 2015). "TMPRSS4 was localized mainly in the cytoplasm or nucleus of primary cancer." (PMID 23922976, 2013). "Nevertheless, the potential mechanism between increased TMPRSS4 expression and cancer progression in TNBC is still unknown." (PMID 23857060, 2013). "In addition, siRNA knockdown of TMPRSS4 in cancer cell lines and in metastatic potential mouse model, reduced cell invasion and migration, thus implying a role for TMPRSS4 in metastasis." (PMID 22692880, 2012). "We next examined TMPRSS4 protein expression in a variety of human cancer cell lines in culture." (PMID 22692880, 2012). "Modulating TMPRSS4 activity may be a treatment for several types of cancer." (PMID 37009799, 2023). "Basically, high TS expression has been shown to result in relatively low sensitivity to fluoropyrimidine-based chemotherapy, including S-1.29, 30 Downregulation of TMPRSS4 may sensitize cancer cells to the cytotoxic effects of S-1 via decreased expression of TS." (PMID 34379296, 2022). "Therefore, we predicted that SLUG or TWIST1 could contribute to TMPRSS4-mediated induction of cancer stem–like properties." (PMID 34809669, 2021). "These previous findings led us to anticipate that TMPRSS4 may modulate cancer cell survival." (PMID 31292507, 2019). "We also showed that TMPRSS4 upregulates the expression of the urokinase-type plasminogen activator (uPA) gene through activator protein-1 (AP-1) and Sp1/3 transcription factors and induces processing of pro-uPA into the active form to promote cancer cell invasion." (PMID 31292507, 2019). "Notably, the relatively high IC50 values of the compounds against TMPRSS4 serine protease activity in vitro compared with those against cancer cell invasion or viability may be partially due to the low specific activity of recombinant TMPRSS4 serine protease." (PMID 31292507, 2019). "It has been implied that TMPRSS4 could be an emerging potential therapeutic target in cancer." (PMID 27344186, 2016). "Several TMPRSS4 specific substrates have been identified thus far, including hemagglutinin of the influenza virus (a protein that is vital for virus infection) and the urokinase-type plasminogen activator (uPA), the latter is important for cancer cell invasion." (PMID 27344186, 2016). "Here, we show systematic profiling of SLC6A20 expressionin pan-cancer tumor and healthy samples together with correlationwith SARS-CoV-2 infection genes ACE2, TMPRSS2, and TMPRSS4 and immunefiltration in tumor samples." (PMID 37041751, 2023). "Using this strategy in NSCLC in the present study, we have found that TMPRSS4 is co-overexpressed with Discoidin Domain Receptor tyrosine kinase 1 (DDR1), a membrane protein that promotes cancer cell growth and dissemination." (PMID 31659178, 2019). "Therefore, TMPRSS4 may be an attractive target for potential anti-cancer therapy." (PMID 31292507, 2019). "TMPRSS4 is highly upregulated in solid tumors (including NSCLC), where it plays a role in facilitating the growth and metastatic spread of cancer cells." (PMID 31817025, 2019). "TMPRSS4, which was initially referred to as TMPRSS39, is strongly upregulated in a variety of cancers." (PMID 31292507, 2019). "It is worth noticing that the degree of promoter methylation found for DDR1 is highly correlated with that of TMPRSS4 in NSCLC patients and cancer cell lines." (PMID 31659178, 2019). "TMPRSS4 is a novel TTSP that is highly expressed in pancreatic, thyroid, lung, colon, and other cancers." (PMID 27385093, 2016).
cancer (continued). "We assessed the mRNA expression level of TMPRSS4 across cancers using two independent databases, the Oncomine and TIMER databases, and found that the expression levels of TMPRSS4 differed in various cancers." (PMID 36380313, 2022). "Mechanistically, TMPRSS4 mainly regulates malignant phenotypes, such as tumor invasion and metastasis, by either the epithelial to mesenchymal transition (EMT) program or promoting the proliferation of cancer cells." (PMID 36380313, 2022). "TMPRSS4, originally referred to as TMPRSS3, is highly upregulated in a variety of cancers." (PMID 34809669, 2021). "Based on the hypothesis that these cooperative genes could be consistently co-expressed in tumors, we searched for TMPRSS4-correlated genes in publicly available genomic data and identified DDR1 among other genes related to cancer cell-ECM interaction." (PMID 31659178, 2019). "Indeed, signaling triggered by both TMPRSS4 and DDR1 in cancer cells activate common pathways, including phosphorylation in ERK1/2 and AKT depending on the cellular context." (PMID 31659178, 2019). "Although the functions of TMPRSS4 is not well established, evidence is accumulating that it promotes cancer progression and EMT of cancer cells." (PMID 29202869, 2017). "The significance of TMPRSS4 overexpression in cancers is not yet clear but is generally believed to promote tumor growth and metastasis." (PMID 22692880, 2012). "TMPRSS4 expression has been studied in several cancers at the transcriptional level but information is lacking on expression of the protein product." (PMID 22692880, 2012). "However, the mechanisms by which TMPRSS4 modulates cancer cell proliferation during tumor progression are not well established." (PMID 27385093, 2016). "Besides the expression of TMPRSS2, TMPRSS4, and TRIM31 in GI cancers, we have analysed the expression of these genes in all cancers, and we have found that the expression of these genes is more upregulated in majority of GI cancers than individual other cancer types." (PMID 35970857, 2022). "Unlike other receptors, such as ACE2, TMPRSS4, and CTSL, increased ISG20 expression may prevent viral invasion in these types of cancer." (PMID 36177004, 2022).
tumor (38 papers, 2008 to 2025). "We showed that high TMPRSS4 expression in tumor tissues was significantly associated with patients' poor OS (pooled HR = 2.981, 95% CI = 2.296-3.869, P < 0.001) and short TTP (pooled HR = 2.456, 95% CI = 1.744-3.458, P < 0.001)." (PMID 27344186, 2016). "High molecular weigh bands corresponding to the 64 kDa marker were observed in three samples suggesting splice-variants of TMPRSS4 in selected primary tumor tissues." (PMID 22692880, 2012). "The 11p11.2 intronic SNP rs12279572 lies within the TMPRSS4 (transmembrane protease, serine 4 isoform-1) gene that encodes a protein implicated in facilitating the invasion, migration and metastasis of human tumor cells via epithelial-mesenchymal transitions." (PMID 21980348, 2011). "Furthermore, TMPRSS4 downregulation was found to be associated with the reducing tumor volume or weight of the subcutaneous xenografts in nude mice." (PMID 33816264, 2021). "Determination of methylation status of TMPRSS4 (TMPRSS4meth status) in blood may be useful in a clinical scenario where a surgically treated patient is at risk based on both stage and high TMPRSS4 tumor expression." (PMID 31817025, 2019). "Moreover, a recent meta-analysis study indicates that high TMPRSS4 expression in solid tumor tissues is associated with poor overall survival and short time to tumor progression." (PMID 29529050, 2018). "Therefore, epigenetic deregulation is likely to be the main cause of TMPRSS4 overexpression in this tumor type." (PMID 26989022, 2016). "Kim developed a novel TMPRSS4-cleavable peptide (TCP)-based liposome (TCP-L) that utilized the proteolytic activity of tumor-overexpressed transmembrane protease TMPRSS4 for targeted drug delivery." (PMID 40573997, 2025). "Another mechanism facilitating EMT and promoting tumor growth and metastasis involves transmembrane serine proteases such as transmembrane protease serine 4 (TMPRSS4)." (PMID 39153052, 2024). "TMPRSS4 contributes to tumor growth and metastatic seeding through diverse molecular mechanisms, thereby linking EMT and tumorigenic programs." (PMID 37009799, 2023). "Transmembrane serine protease 4 (TMPRSS4) is a cell surface anchored serine protease that promotes resistance to anoikis, tumor sphere formation, and therapeutic resistance of PCa cells." (PMID 36300093, 2022). "Functionally, dysregulated TMPRSS4 mainly controled cell biological behavior and results in tumor proliferation, invasion, and migration phenotype." (PMID 36380313, 2022). "The expression of TMPRSS4 was positively correlated with the depth of tumor (T) and venous (V) invasion." (PMID 34379296, 2022). "Regarding the tumor location, the TMPRSS4-positive cells were higher in the proximal site than the distal site of stomach without any significance." (PMID 34379296, 2022). "In this study, we for the first time analyzed the expression level of TMPRSS4 and investigated its correlation with clinical pathological characteristics and tumor immune cell infiltration to assess its prognostic value in TC." (PMID 36380313, 2022). "TMPRSS4 was positively correlated with tumor immune infiltration and the expression of gene markers of immune cells." (PMID 36380313, 2022). "We further evaluated the correlation of TMPRSS4 expression with the markers of each tumor infiltrating immune cells in TC from the TIMER2.0 database." (PMID 36380313, 2022). "Our results not only offer new insights into the function of TMPRSS4 in TC but also highlight a possible molecular mechanism of the interaction between TMPRSS4, immune cells and tumor cells." (PMID 36380313, 2022). "Our results showed that the expression of TMPRSS4 is significantly correlated with deeper tumor and venous invasion." (PMID 34379296, 2022). "In regard to OS, the univariate analysis revealed that TMPRSS4, tumor size, deeper tumor invasion, lymph node metastasis, venous invasion, lymphatic invasion, invasion type, and stages of tumor were all significant prognostic factors for OS." (PMID 34379296, 2022).
tumor (continued). "Recent studies suggest that TMPRSS4 facilitates cancerous tumor growth and metastasis in multiple malignancies." (PMID 33816264, 2021). "In the current study, real-time qPCR, immunohistochemical staining, Western blotting, and database (Cancer Genome Atlas and Gene Expression) analysis revealed remarkable overexpression of TMPRSS4 in PDAC tissue as compared to non-tumor tissue." (PMID 33816264, 2021). "Our previous and present studies showed that TMPRSS4 contributes to tumor progression through diverse molecular mechanisms, linking the EMT and tumorigenic programs." (PMID 34809669, 2021). "The expression of CORO1C and TMPRSS4 in normal bladder tissues and the relationship between two genes and tumor stage were explored via GEPIA online tool." (PMID 32695668, 2020). "We next used plasma from 89 patients with NSCLC and 25 tumor-free individuals (controls) for the study of both TMPRSS4 and SHOX2 methylation by ddPCR (1 mL for each gene)." (PMID 31817025, 2019). "Previously, we demonstrated that TMPRSS4 mediates tumor cell invasion, migration, proliferation, and metastasis." (PMID 31292507, 2019). "When stable DU145 cells were injected into nude mice, tumor growth was significantly increased in mouse xenografts with TMPRSS4-overexpressing DU145 cells compared with vector-transfectants, consistent with in vitro results." (PMID 31292507, 2019). "The next step was to quantify the methylation status of the TMPRSS4 promoter by ddPCR in tumor samples from NSCLC patients, in order to validate our previous results using pyrosequencing and 450k arrays, which showed hypomethylation of cg25116503 in tumors." (PMID 31817025, 2019). "Two TMPRSS4-specific compounds were recently shown to inhibit protein activity and tumor growth in prostate cancer models." (PMID 31817025, 2019). "Tumor growth was significantly increased in mouse xenografts with TMPRSS4-overexpressing cells compared with vector transfectants." (PMID 27385093, 2016). "Existing evidences have reported an important role of TMPRSS4 in cell motility, invasion, proliferation and tumor metastasis." (PMID 27344186, 2016). "Because cell migration promotes tumor invasion, we tested the effect of TMPRSS4 knockdown on cell invasion using Matrigel-coated Transwell chambers." (PMID 26993610, 2016). "More important, in clinical HCC specimens, TMPRSS4 expression was significantly correlated with tumor staging and was inversely correlated with E-cadherin and RECKS expression." (PMID 26190376, 2015). "TMPRSS4 protein was detected in 14 of 92 (15.22%) human non-tumor mucosa samples, and all samples expressed the protein at a low level." (PMID 23922976, 2013). "Hypoxia is known to prevail in the tumor micro-environment and was therefore tested as a potential regulator of TMPRSS4 protein expression." (PMID 22692880, 2012). "In both types of tumor, >70 and 59% of samples showed 3- and 5-fold or greater TMPRSS4 mRNA expression than normal lung tissue, respectively." (PMID 22692880, 2012). "In contrast, tail vein injection of H358 tumor cells knocked-down for expression of TMPRSS4 with shRNA resulted in decreased tumor metastasis to the lung." (PMID 22692880, 2012). "The average relative TMPRSS4 expression was calculated in comparison with 18S ribosomal RNA and plotted by tumor subtype." (PMID 22692880, 2012). "This observed discrepancy in TMPRSS4 expression between primary tumor samples and tumor cell lines cultured in vitro suggested an influence of the environment on protein expression." (PMID 22692880, 2012). "The 51-kDa protein band failed to migrate uniformly in all samples, another indication of proteolysis or post-translation modification of TMPRSS4 in the tumor specimens." (PMID 22692880, 2012). "Staining of over 100 NSCLC primary tumor and normal specimens with rabbit polyclonal anti-TMPRSS4 antibodies confirmed expression at the protein level in both squamous cell and adenocarcinomas with little or no staining in normal lung tissues." (PMID 22692880, 2012).